KIT (KIT proto-oncogene, receptor tyrosine kinase)
Diseases named in the same sentence as KIT in open-access papers (continued):
Sharing a sentence is not in itself a finding about the gene and the disease.
tumor (continued). "We stratified DOG1 positive patients in relation to the Allred scoring system to identify those with a higher risk of recurrence; in our study patients with a strong DOG1 expression, tumor size ≥ 5 cm and mutations of KIT or PDGFRA had a worse prognosis." (PMID 26867653, 2016). "The following items were collected from each study: first author’s name, year of publication, number of patients, countries, the number of mitosis per 50 HPFs in GIST, tumor size, c-KIT mutation, treatment and the time of follow-up." (PMID 26349547, 2015). "The studied tumour harboured two typical genomic lesions: loss of the long arm of chromosome 14 and an activating mutation in exon 11 of KIT." (PMID 26102504, 2015). "Taken together, our study indicated that KIT mutation status is another evaluable factor to estimate prognosis in GISTs in addition to tumor size and mitotic counts." (PMID 26349547, 2015). "Characteristically these neoplasms contain activating mutations in KIT, or less commonly platelet derived growth factor receptor alpha (PDGFRA)." (PMID 25694839, 2015). "In the 11 primary tumour samples with secondary KIT exon 13 mutation (c.1961 T > C, p.V654A) in the recurrent tumour, minor percentages were seen with the GS Junior (Roche)." (PMID 25886408, 2015). "In order to tell founding from passenger mutations, we looked for mutations approximately as frequent in the tumour as the KIT mutation." (PMID 26102504, 2015). "The discovery that the vast majority of GISTs have characteristic activating mutations in c-KIT (75–80%) or PDGFRA (5–15%) radically changed the management of these tumours by the approval of the use of tyrosine-kinase inhibitors." (PMID 26075122, 2015). "In 1998, Hirota and colleagues identified a gain-of-function mutation in the c-KIT gene that characterized this tumor." (PMID 25885906, 2015). "Mutated KIT is a major driver of tumor growth in GIST cancer and is very potently inhibited by regorafenib." (PMID 26599335, 2015). "The activation of KIT is associated with tumor proliferation, differentiation, adhesion, and apoptosis." (PMID 25963410, 2015). "GISTs are thought to derive from a precursor of the interstitial cells of Cajal, which express a transmembrane receptor tyrosine kinase encoded by the KIT gene, and almost all GISTs express activating mutations in KIT that promote tumor survival and growth." (PMID 26646242, 2015). "Focusing on the epidemiology of this type of neoplasm, our purpose is to define the distribution of KIT, PDGFR-alpha and BRAF mutations in a population-based cohort of GIST and correlate them with risk classifications and survival." (PMID 25885906, 2015). "In the future, the stratified analysis by tumor size and mitosis index should be carried out to identify the prognosis power of KIT mutation, because tumor size and mitosis index are the most important confounding factors." (PMID 26349547, 2015). "These patients have a spectrum of neoplastic disease ranging from benign to malignant, depending on the tumor size, mitotic activity, anatomic site of origin and the presence of a KIT mutation." (PMID 25609545, 2014). "In KIT, four single nucleotide polymorphisms (SNPs) were found in exon 14, 15, 19 and 20 (11% each) in each of 4 different tumours." (PMID 25413220, 2014). "GISTs are typically defined by the expression of c-KIT (CD117) in the tumor cells, as these activating KIT mutations are seen in 85–95% of GISTs." (PMID 24963404, 2014). "We established a novel human GIST xenograft, UZLX-GIST9, harbouring KIT exon 11 and 17 mutations and maintaining the pheno-and genotype of the original tumour." (PMID 25132955, 2014). "Unfortunately, patients often develop secondary resistance to imatinib mesylate within 2 years of treatment, likely due to the presence of new KIT mutations in existing tumor cells." (PMID 25609545, 2014).
tumor (continued). "Mutations in the 9th and 11th exons of the KIT gene were observed in the first tumor, whereas a mutation in the 9th exon of the KIT gene was present in the second tumor." (PMID 24678982, 2014). "Genetic sequencing analyses revealed that two tumors had KIT exon 9 mutations and one tumor had an exon 11 mutation." (PMID 24507750, 2014). "In this retrospective study, tumor mutational testing for the oncogenic KIT and/or PDGFRA genes was able to be performed in only 12 of 41 (29%) of these rare patients with rectal GISTs." (PMID 24597959, 2014). "The exact diagnosis and tumor origin of GISTs were difficult to determine until the discovery of the gain-of-function mutation in the KIT oncogene." (PMID 24548660, 2014). "When RTK expression was adjusted for known tumor characteristics, the significant correlations for c-KIT and VEGFR2 expression were retained whereas the association between PDGFRα and TNBC was not significant." (PMID 25025175, 2014). "Gain-of-function mutations in c-KIT leading to pathologic activation are seen in several neoplasms, such as GISTs and acute myeloid leukemia." (PMID 25025175, 2014). "KIT mutations in exons 9, 13 and 17 are less common and have been associated with more aggressive tumor behavior." (PMID 24119564, 2013). "Patterns of mRNA and miRNA expression in cells and tumours depend on heterozygous/hemizygous status of KIT mutations, and deletion/presence of TYR568 & TYR570 residues." (PMID 23593401, 2013). "Oncogenic mutations in KIT or PDGFRA have been identified as central tumor-initiating events in many GISTs." (PMID 23902675, 2013). "KIT remains a key diagnostic marker for this tumor type, and mutant KIT and PDGFRA proteins have become crucial therapeutic targets in GISTs." (PMID 23153013, 2012). "This mutation results in a constitutively activated KIT tyrosine kinase and leads to increased malignant behaviour in most affected tumours." (PMID 22747577, 2012). "A similar lack of correlation between baseline sKIT levels and clinical outcomes was reported in GIST, a tumor type in which activating mutations yielding constitutively active KIT proteins occur in approximately 80% of tumors." (PMID 22897944, 2012). "As for imatinib, KIT mutation status appears to serve as a predictor of tumor response to sunitinib." (PMID 22439647, 2012). "GISTs are clinically and histologically heterogenous neoplasms that are driven by oncogenic KIT or PDGFRA mutations." (PMID 21559207, 2011). "Our previous retrospective study showed that the presence of KIT mutations, along with a high mitotic rate and larger tumor size, was an independent risk factor for poor prognosis in patients with localized GIST." (PMID 21975443, 2011). "The estimated median survival was 63 months for patients whose tumor harbored a KIT exon 11 mutation, 44 months for patients whose tumors harbored a KIT exon 9 mutation and 26 months in case of other mutations or WT GIST." (PMID 21605429, 2011). "KIT shows the lowest clustering value because it is only rarely mutated in the eight selected tumor types and the mutations are even more scattered in the structure than random." (PMID 21575214, 2011). "The 87.5% of patients whose tumor had a KIT exon 11 mutation achieved a partial response, whereas only 47.8% of patients whose tumor had a KIT exon 9 mutation had a partial response." (PMID 21605429, 2011). "Tumor endothelial cell KIT expression was highly significantly associated with endothelial cell phospho‐KIT expression (P = 0.0009), suggesting that endothelial cell KIT was often activated." (PMID 20030644, 2010).
tumor (continued). "Tumor cell phospho‐KIT expression was associated with endothelial cell KIT expression (P = 0.011), and tumor cell SCF expression with endothelial cell SCF expression (P = 0.029)." (PMID 20030644, 2010). "Further studies are needed to investigate associations between tumor necrosis, histological grade and endothelial cell KIT expression in different types of human cancer, and the related molecular biological mechanisms." (PMID 20030644, 2010). "Three (30%) tumours were found to harbour the KIT exon 10 mutation, including the patient with CR (13 months +) and two patients with SD." (PMID 20664593, 2010). "Yet, tumor cell expression of VEGFR‐2 was associated with endothelial cell expression of KIT, phosphorylated KIT and SCF." (PMID 20030644, 2010). "Tumors with PDGFRA mutations showed the same overall pattern of alterations seen in those with KIT mutations, even if genomic complexity was much lower in the former (median of 2 vs. 5.5 alterations per tumor, respectively, P = 0.050, Mann-Whitney U test)." (PMID 20470368, 2010). "In 14 out of 15 GISTs with a KIT mutation and in 2 out of 10 GISTs with a PDGFRA mutation, the relative expression of KIT was 1.47 arbitrary units (a.u.)or greater, while in the remaining tumours, it was 0.37 a.u. or lower." (PMID 19943934, 2009). "We selected a model of gastric GIST to obtain a balanced set of tumours with mutations in either KIT or PDGFRA." (PMID 19943934, 2009). "Among the probe sets with detectable expression levels, the non-parametric Kruskal-Wallis test revealed 970 (311 with FC>2; FC = fold change) probe sets differentially expressed between tumours with KIT and PDGFRA mutations." (PMID 19943934, 2009). "This analysis identified significantly lower expression of PKC-alpha and significantly higher expression of PKC-theta in tumours with KIT mutations compared to those with PDGFRA mutations or wild-type tumours." (PMID 19943934, 2009). "Genotyping revealed that 15 tumours had KIT mutations (14 in exon 11 and one in exon 9), 11 tumours had PDGFRA mutations (9 in exon 18 and two in exon 12), and 3 were KIT/PDGFRA wild-type GISTs within the analyzed mutation hotspots." (PMID 19943934, 2009). "Of these 311 (FC>2), 109 probe sets (81 genes) were upregulated, and 202 probe sets (143 genes) were downregulated in samples from tumours harbouring KIT mutations compared to those with PDGFRA mutations." (PMID 19943934, 2009). "Among the five tumours with KIT gene mutation of exon 11, four (80%) tumours showed strong (++++) and one showed (20%) high (+++) c-KIT protein expression." (PMID 19018266, 2008). "In our patient cohort, which was representative for an unselected GIST population with regard to sex, age, tumour localisation, histology, risk classification, and KIT exon 11 mutations, Fas and FasL were abundantly expressed." (PMID 18941456, 2008). "The variables Ki67 max%, tumour size and deletion of KIT exon 11 allow us to formulate a risk score for tumour recurrence, which equals the linear combination of the three variables with the weighted β-coefficients." (PMID 17519908, 2007). "The basal-like group was subsequently defined, using immunohistochemistry, as being ER- PR- ERBB2-, with tumor cells expressing at least one basal-myoepithelial marker such as KRT 5/6 or KRT 14 in association with EGFR or KIT." (PMID 17417968, 2007). "It appears that c-KIT gene mutations are pivotal molecular events in the life of these tumours, adversely affecting their overall prognosis after surgery." (PMID 17029627, 2006). "In recent years, c-KIT has been implicated in the pathogenesis of canine cutaneous mast cell tumors (MCTs), which are one of the most common neoplasms in dogs." (PMID 16579858, 2006). "This issue is complex, since although most GISTs acquire a gain-of-function c-KIT mutation, many tumours ultimately demonstrate some resistance to targeted molecular therapy during treatment." (PMID 17029627, 2006).
tumor (continued). "The GISTs are often characterized by expression levels of KIT, a tyrosine kinase, and many tumours contain mutations of the KIT-encoding gene, c-kit." (PMID 15150562, 2004). "The treatment was found to be safe and particularly effective in tumours with activating mutations of exon 11 of the KIT gene." (PMID 12888812, 2003). "Here we show that the over-expression of an additional potentially antiapoptotic gene, the c-KIT gene, is associated with this tumour." (PMID 11487273, 2001). "Namely, mutations of KIT have been described in 10% of TC cases, and KIT inhibitors have been reported to be efficacious in these patients, showing proof of concept regarding its role in driving tumor growth and progression." (PMID 39996868, 2025). "We could not find a correlation between the establishment of a model and the type of mutation (primary KIT versus secondary KIT versus PDGFRA versus other mutations) of the tumor sample." (PMID 39853155, 2025). "If KIT mutations alter the rate of tumor progression in vivo, the F436S mutation could also be used as a prognostic factor." (PMID 40427321, 2025). "It is likely that more aggressive tumor subclones overcome the treatment, mostly owing to secondary, resistant KIT mutations, and these remaining cells after TKI treatment might be sufficient for further tumor growth in the laboratory mice." (PMID 39853155, 2025). "It targets several receptors implicated in tumor growth and angiogenesis, including KIT, VEGFR2 (KDR), VEGFR3 (FLT4), and FLT3, making it a candidate for treating GISTs, particularly in patients who have developed resistance to standard therapies like imatinib." (PMID 40733131, 2025). "In contrast, perimembranous KIT immunostaining (pattern I), as seen in the case here described, is associated with a more favorable prognosis in dogs, with low risk of recurrence, distant metastases and tumor-related death." (PMID 41415727, 2025). "Our results suggest strengthening the monitoring of young patients with primary tumors in the small intestine and those with high-risk tumors or KIT exon 9 insertion or KIT exon 11 deletions at time of diagnosis to ensure early detection of potential tumor progression and timely treatment." (PMID 40377443, 2025). "The response rates of KIT inhibitors seem to be enhanced in patients with KIT-mutant mucosal tumours particularly in exons 11 and 13 with mutations of exon 17 associated with lower progression free survival in multi-variate analysis of prospective and retrospective trials." (PMID 41295253, 2025). "Thus, PCTSs from tumours with c-KIT mutations were considered imatinib-sensitive, while PCTSs from tumours with PDGFRA mutations were expected to be imatinib-resistant." (PMID 41373613, 2025). "The study incorporated circulating tumor DNA (ctDNA) analysis to monitor KIT mutations." (PMID 40733131, 2025). "Although KIT Exon 13 mutations have been reported in several retrospective studies and case series, they are typically described in the context of tumor location, response to therapy, or familial inheritance, and rarely in association with hematologic abnormalities." (PMID 40837560, 2025). "Numerous studies have substantiated that several factors may contribute to poor prognosis in GIST, including tumor rupture, positive surgical margins, KIT exon 11 mutations, and gastrointestinal hemorrhage." (PMID 41293170, 2025). "Importantly, NGS on the tumor samples identified a pathogenic KIT exon 11 deletion (p.K558_V560del) with 63.80% variant allele frequency (VAF)." (PMID 40900786, 2025). "Furthermore, the high risk group was primarily enriched in GRN, TWEAK, and KIT tumor-related signaling pathways." (PMID 41211507, 2025). "Furthermore, ripretinib shows efficacy against other tumor types harboring KIT or PDGFRA mutations, including mastocytosis, leukemia, and lung cancer." (PMID 40231257, 2025).
tumor (continued). "Second, the data in this study came from the Seer database, and some of the variables lacked details, such as the specific type of surgery, the size and number of liver metastases, the detailed chemotherapy regimen and dose, chemotherapy responsiveness, and tumor KIT or PDGFRA mutation information." (PMID 38347834, 2024). "These mutations activate the KIT tyrosine kinase receptor, driving tumor growth and survival." (PMID 39200315, 2024). "Mutated KIT copy number (mK-CN; measured on baseline biopsy sample) tumor values (see STAR Methods), reflecting copy-number status of the KIT gene, could be inferred in 22 evaluable patients in baseline tumor samples." (PMID 38417447, 2024). "These tumor volumes were lower compared to the tumor volume at week 221 (855.2 mL) in which the primary KIT exon 11 mutation could be detected in cfDNA." (PMID 38790141, 2024). "In addition, in the present case, the differences between KIT expression patterns and KIT mutation status appeared to be linked to the tumour location." (PMID 39177283, 2024). "The KIT exon 11 mutation was detectable in cfDNA at baseline, when the tumor volume was 2563.3 mL." (PMID 38790141, 2024). "Overall, we expanded the knowledge on the KIT mutational spectrum of these tumor types." (PMID 39728933, 2024). "CCDC26 knockdown could cause imatinib resistance in gastrointestinal stromal tumor cells through decreasing c-KIT expression." (PMID 38431660, 2024). "The type and location of KIT exon 11 mutations are linked to specific tumor phenotypes." (PMID 37046734, 2023). "Another potential target that could be linked with PD-1 resistance might include KIT as an important player in the tumor microenvironment." (PMID 37740836, 2023). "Furthermore, the presence of a mutation in the c-KIT gene (KIT) has been related to tumor development in MCT cases." (PMID 37370399, 2023). "Most oncogenic KIT variants identified in human neoplasms occur in mutational hot spots." (PMID 37025992, 2023). "After complete resection, adjuvant therapy with imatinib for 3 years is the standard of care in patients with a high risk of recurrence (risk assessed by mitotic index, neoplasm size, anatomical site, and rupture of the tumor at the time of surgery) and KIT or PDGFR-α sensitive mutation." (PMID 37888038, 2023). "In GIST, positive expression of Stem Cell Growth Factor (SCGF) has been associated with response to the tyrosine kinase inhibitor imatinib, and exosomal expression of proteins Sprouty homolog 4 (SPRY4) and tyrosine protein kinase KIT have been associated with increased risk of tumor progression." (PMID 37197427, 2023). "In cases of tumor progression on imatinib 400 mg per day, an option may be to increase the imatinib dose to 800 mg per day orally in patients with KIT exon 11 mutation." (PMID 37046734, 2023). "Secondary KIT mutations in GISTs are commonly identified in post-imatinib biopsy specimens of patients who underwent first-line therapy with imatinib and should be related to the selective pressure exerted on tumor cells by the primary treatment." (PMID 37046997, 2023). "We found an association between KIT expression pattern and tumor recurrence rates." (PMID 36670824, 2023). "The KIT mutations found in our plasma analyses were then compared to tumor samples." (PMID 36428589, 2022). "Tumor-related gene KIT, was also detected to have a somatic variant." (PMID 36026497, 2022). "However, canine PC cells can induce cell proliferation mediated by autophosphorylation by exhibiting high transcriptional levels of c-KIT, but its expression in this neoplasm cannot be associated with the metastatic process in individuals of this species." (PMID 35681707, 2022). "As expected from our in vitro studies, HHT-treated tumor cells showed a loss of KIT expression." (PMID 35585158, 2022). "Higher expression of KIT in TNBC is associated with larger tumours and lymphovascular invasion." (PMID 34718356, 2022).